CXCL10 (C-X-C motif chemokine ligand 10)
Diseases named in the same sentence as CXCL10 in open-access papers (continued):
Sharing a sentence is not in itself a finding about the gene and the disease.
infection (1,601 papers, 2005 to 2026). The state of being infected such as from the introduction of a foreign agent such as serum, vaccine, antigenic substance or organism. "During acute inflammation caused by PCN033 infection, Cxcl9, Cxcl10 and Cxcl11 induction recruits immune cells for PCN033 clearance." (PMID 41295668, 2025). "Infection was associated with the upregulation of proinflammatory genes CXCL10, IFNG, and IL15, alongside several NK and T cell activation markers such as CD244, CD40LG, and CD226." (PMID 39774119, 2025). "This first description of the dynamics of HPV infections comes with the identification of immune correlates associated with infection clearance, especially gamma-delta T cells and CXCL10 concentration." (PMID 39836629, 2025). "Regarding the cytokines, the strongest signal was that infections with higher culmulative viral burden were significantly associated with decreased CXCL10 concentrations." (PMID 39836629, 2025). "As a consequence, we find an association between innate immune effectors such as CXCL10 and milder infections." (PMID 39836629, 2025). "PBEC were able to be infected with IAV and infection caused an increase in expression of immune genes including CXCL10, IFNB1, ISG15 and SOCS1." (PMID 40496017, 2025). "A striking pattern in our results is that some hallmarks of the innate immune response, such as CXCL10, are associated with milder infections." (PMID 39836629, 2025). "These analyses highlighted a conserved response to infection associated with chemokines (Cxcl10, Ccl2) and cytokines (interferon signaling)." (PMID 40444956, 2025). "The protein expression of three proteins (IL-8, CXCL9, and CXCL10) were significantly increased in caspase-4-deficient cells compared to Cas9 cells following HK1651 infection." (PMID 40137780, 2025). "Pre-infection samples from SE donors showed modestly lower type I interferon gene expression and reduced CXCL10 protein levels, which was inversely associated with post-infection viral load in a log-linear manner." (PMID 41279354, 2025). "The effect of baricitinib was similar to ruxolitinib, causing a significant increase in antibody-mediated infection of macrophages by both delta and omicron viruses, and a concomitant significant decrease in the production of IFNα and CXCL10." (PMID 39737903, 2024). "Infection with the Beta variant had little impact on the production of Interferon γ-induced protein 10/IP-10 (C-X-C motif chemokine ligand 10/CXCL-10) and tumor necrosis factor-α (TNF-α), and resulted in a significant increase in Interleukin 6 (IL-6) levels." (PMID 38568894, 2024). "Upon infection with rSFV particles encoding CXCL10, Flt3L or IFN-ƴ, both LNCaP and PANC-1 cells were observed to produce and secrete high amounts of the respective cytokines, detectable from 6 h post-infection." (PMID 38425844, 2024). "Additional cytokine/chemokine transcripts induced by invasive infection were e.g., Ccl3, Ccl4, Ccl7, Cxcl10, and Csf2 (encoding GM-CSF)." (PMID 38291037, 2024). "Upon infection with all variants, the evaluated ISGs, Cxcl10, Isg15, and Mx-1, were upregulated and the expression levels for B.1.1 were the highest, followed by those for BA.2 and BA.5 in the lung hilum area." (PMID 37488344, 2023). "Among these chemokines, the CXCL10 produced during infection by intestinal ECs is associated with the recruitment of DCs, resulting in a protective immune response in neonatal mice." (PMID 37110479, 2023). "They reported that 5 cytokines, including CXCL10, were associated with fatal outcomes during infection." (PMID 37026002, 2023). "On the other hand, CXCL10 was found to promote the infection caused by the human immunodeficiency virus (HIV) by stimulating the virus replication in macrophages and lymphocytes." (PMID 36366543, 2022). "In serum, there was a lower induction of CCL2 and CXCL10 during the early stages of infection in beta variant-infected mice." (PMID 36005818, 2022).
infection (continued). "Alterations in CXCL10 expression have been associated with inflammatory diseases (including infections), immune dysfunction, and the development of tumors." (PMID 35464491, 2022). "In short, the expression of CXCL10 was differentially associated with clinical symptoms in multiple infections." (PMID 36366543, 2022). "CXCL10 is also known to play a critical role in the host defense against infection caused by the John Howard Mueller (JHM) strain of mouse hepatitis virus (JHMV)." (PMID 36366543, 2022). "The levels of the pro-inflammatory cytokine CXCL10 measured in the blood had a positive association with the infection frequency of genetically-intact HIV, and this association approached statistical significance (P = 0.08)." (PMID 35916523, 2022). "Among death causes, a higher percentage of infections as cause of death was observed after heart transplant in high IL-6/CXCL10 category." (PMID 33758270, 2021). "As a critical factor in immune activation through paracrine signaling, the decreasing of CXCL10 showed that immune cell differentiation was weakened, and the cattle susceptible to infection by germs." (PMID 33643382, 2021). "Other transcripts encoding pro-inflammatory genes identified as up-regulated in response to sublethal PVM infection and down-regulated in response to L. plantarum include those encoding Ccl2, Ccl8, Cxcl9, Cxcl10, and resistin-like molecule alpha (Retnla)." (PMID 34959580, 2021). "In a mouse model with impairment of ISGF3 signaling, H. pylori led to decreased CXCL10 responses and increased susceptibility to infection." (PMID 33503840, 2021). "As mentioned, four of these cytokines (IL-1α, IL-6, IL-8 and CXCL10) are associated with activation of the innate immune response to infection." (PMID 33657181, 2021). "Reported associations of CCL2, CXCL9 and CXCL10 polymorphisms with the incidence of infection and severity of SARS have been inconsistent." (PMID 33613280, 2020). "CXCL10 has been associated with both protective and pathological infections depending on the infection and host immune status." (PMID 32226041, 2020). "For example, a study of mice with different susceptibilities to TBEV infection revealed that higher CXCL10 expression in the brain correlated with more severe course of infection and poorer outcome." (PMID 31699097, 2019). "This gene encodes one of proinflammatory chemokine CXCL10 attracting leukocytes to the site of infection." (PMID 29882085, 2018). "CXCL10 is already an established biomarker for TB, where high levels are associated with extent of infection and treatment efficacy." (PMID 30026741, 2018). "This study evaluated the potential of CXCL10 in controlling infection caused by L. infantum using in vitro and in vivo models of VL." (PMID 28767981, 2017). "This was despite increased expression of T-cellchemoattractant Cxcl9 and Cxcl10 in M-TNFR1 KO mice 3–5weeks post-infection, likely linked to the increased neutrophil population in thesemice." (PMID 26931771, 2016). "At 4 weeks post-infection, Th1-associated Ifng, Cxcl10, and Il12 transcript levels were significantly higher in joints of Il10-/- and DKO mice, compared to transcript levels in joints of B6 and Mir155-/- mice." (PMID 26252010, 2015). "Transcript levels of other Lyme arthritis-associated genes (IFNγ, Cxcl10, TNFα) were very similar between the two strains, and showed a peak in expression at 2 weeks post-infection, followed by resolution at 4 weeks." (PMID 24967703, 2014). "Infection of mice with VACV vΔC16 caused enhanced production of the chemokine Cxcl10 and the cytokine Il-6 in the lungs." (PMID 24098118, 2013). "Our results represent a clear association between the infection with CagA+ strains of H. pylori and the serum levels of chemokine CXCL10." (PMID 23467184, 2013). "Fas and FasL-deficient mice showed significantly less percentages of CXCL10 - expressing monocytes at 7 day of infection (p≤0.01) in comparison to HSV-2 infected wild-type strain." (PMID 23922974, 2013).
infection (continued). "DENV-triggered expression of CXCL10 recruits NK cells to the liver which cause liver cell death early after infection." (PMID 23050007, 2012). "In response to P. aeruginosa, genes associated with IFN-γ response to infection (CXCL10, IL-24, IFNγR2) and other mediators of anti-infectious responses (CSF2, MMP1, MMP3, TLR2, S100 calcium-binding proteins A) were markedly up-regulated in wild-type TG cells." (PMID 19399182, 2009). "Notably, infection with all SARS-CoV-2 variants led to a significant induction of IP-10/CXCL10 in Calu-3 cells, with the highest expression observed following infection with the Delta variant." (PMID 38568894, 2024). "CXCL10 is produced by many cells, including endothelial cells, hepatocytes, and astrocytes, and is implicated both in recruitment of cells to the original site of infection, but also across the BBB and into the brain, inducing CM progression." (PMID 36844403, 2023). "Moreover, CXCL10 limits the spread of infection, contributing to early host defense and associated with a direct anti-viral effect against several RNA viruses." (PMID 36366543, 2022). "With RANTES, CXCL10, and CXCL11, most of these targets have also been upregulated in apical secretions of primary human Fallopian epithelial cells 48 h post Ct infection; and CXCL10 and CXCL11 have also been associated with the increased risk of Ct reinfection in women." (PMID 34684219, 2021). "Transcription of type I and III IFNs and C-X-C motif chemokine 10 (CXCL10) genes also revealed species specific expression patterns that may be associated with the differences in the outcome of infection." (PMID 32226041, 2020). "Indeed, genes within the IL-17 pathway including Cebpb, Tnf, IL-6, Cxcl1, Cxcl2, Cxcl3, Cxcl5, Cxcl10, and Ccl7 were shown to be up-regulated in both susceptible and resistant mice during infection." (PMID 29339782, 2018). "Furthermore, Fas and FasL-deficient mice showed significantly lower levels of CXCL10 production at 7 day of infection in comparison to HSV-2 infected wild-type strain (p≤0.01)." (PMID 23922974, 2013). "Moreover, our results demonstrate induction of CXCL10 in vivo in different organs of NiV-infected hamsters, as well as in patients that succumbed to lethal NiV-infection, thus revealing an important association between NiV-infection and CXCL10 production." (PMID 22393386, 2012). "However, CXCL10 remains dispensable for T cell infiltration or the development of fatal inflammation during infection with LCMV (Armstrong), further highlighting underlying differences in viral strains and chemokine utilization with regards to disease outcome." (PMID 20686655, 2010). "In a study of host responses to oral transmission of SIV, high CXCL9 and CXCL10 levels in lymph nodes after infection were associated with rapid progression of disease, whereas high levels of these chemokines in the oral mucosa were associated with slow progression of disease." (PMID 19149556, 2009). "Given the importance of persistent inflammation and immune activation in the pathogenesis of post-COVID lung damage, we evaluated whether levels of anti-SARS-CoV-2 IgG and the pro-inflammatory chemokines CXCL9 and CXCL10 were associated with pulmonary sequelae at four months post-infection." (PMID 41425601, 2025). "The most notable findings were increased levels of CCL2 and CXCL10 pro-inflammatory chemokine protein and mRNA levels in brain homogenates by enzyme-linked immunosorbent assay (ELISA) and reverse transcriptase quantitative PCR (RT-qPCR) assays, respectively, upon infection." (PMID 39745442, 2025). "In addition, upregulation of molecules related to cellular apoptosis pathways, the NF-κB pathway, cell death, and tissue injury caused by the infection was observed, and there was activation of antiviral response pathways marked by the production of cytokines such as CXCL10 and IFN type I." (PMID 36366521, 2022).
infection (continued). "As early as wk 3 post infection we were able to observe distinct transcriptional profiles in infected mice compared to naïve controls including increased expression of chemokines (Cxcl9 and Cxcl10) and genes associated with MHCII expression (H2-Aa, H2-Ab1 and H2-Eb1)." (PMID 35958580, 2022). "Here, we report that a deficiency in CXCL10, which is a chemoattractant for monocytes/macrophages/T cells, led to the same viremia as wild-type animals, but fewer immune infiltrates and lower viral loads in footpads at the peak of arthritic disease (6–8 days post infection)." (PMID 33147869, 2020). "Hence, we quantified the expression of various immunity-related genes regulated by NF-κB: IFNß, CXCL2, TNF, CCL5 and CXCL10 in the brain of mice from two genetic backgrounds, at late stage of the infection by Tha or the isogenic Th4M virus mutated on the positions 77, 100, 104, 110 of the M protein." (PMID 29084252, 2017). "Dynamic infection-responsive genes, including CXCL10, CXCL11 and IL15, exhibited robust antiviral signatures, which highlighted Mac_CD163 as key cellular mediators in the immune response to ASF." (PMID 42216858, 2026). "CXCL9 and CXCL10 are significantly increased (~250-fold) in the plasma profiles of PWH compared to pre-infection levels." (PMID 41516395, 2026). "Cytokine profiling revealed an acute Th1-skewed response, with elevations in CXCL9, CXCL10, IL-27, IFNγ, IL-12, and IL-18 during early infection." (PMID 41636514, 2026). "Results showed elevated levels of pro-inflammatory cytokines such as TNF-α, IL-6, IL-1β, and chemokines CCL5 (RANTES), and IP-10 (CXCL10) after infection with rHPh-TX H5N1." (PMID 40712003, 2025). "SGE-enhanced dissemination of virus to joint tissues resulted in higher upregulation of key arthritogenic cytokine transcripts, including TNF-alpha and IL-6, and the chemokines CXCL2, CCL2, and CXCL10 at day 7 post infection." (PMID 41362756, 2025). "We measured protein concentrations of interferon-beta (IFNβ), interferon-lambda-2 (IFN-λ2/IL-28A), interferon-lambda-3 (IFN-λ3/IL-28B), and the interferon-stimulated chemokine CXCL10 in supernatant from BECs pre-infection and 2-days following RV infection." (PMID 41279354, 2025). "In contrast, CXCL10 was readily detected with broad dynamic range in pre- and post-infection samples and was therefore used as a surrogate protein marker of IFN tone." (PMID 41279354, 2025). "After infection, the expression levels of CXCL10, Saa3, and CCL7 were found to be elevated across all viral-infected groups." (PMID 40338080, 2025). "CXCL10 regulates the migration and spatial localization of immune cells within tissues, thereby playing a pivotal role in the innate immune response during infection." (PMID 41476984, 2025). "CXCL10 secretion initiates around 8 hours post-infection, coinciding with the timing of DC migration to lymphoid organs, thereby facilitating a targeted immune response." (PMID 40825006, 2025). "Early in infection, M3 decreased the expression of CXCL10 and CCL5 mRNAs, whereas BXA also increased their expression, indicating that these mRNAs, which are targets for M3, can be a source of m7G caps." (PMID 39601535, 2025). "Conversely, infection-induced upregulation of CXCL10, STEAP4, C3 and GFAP was significantly reduced in CK2βVas-/- mice." (PMID 40929057, 2025). "CXCL10 plays a crucial function in stimulating migration, and infiltrating certain subsets of T lymphocytes at the infection sites during a viral infection." (PMID 40181980, 2025). "We also showed that PNAG induces the formation of CD14 + CXCL10+ monocytes that can migrate to the site of infection, triggering an innate immune response against S. aureus." (PMID 40745039, 2025). "Increased Cxcl9 and Cxcl10 are in line with observations during infection and vaccination where IFN-I signaling is suppressed and chemokine transcription remained elevated." (PMID 40062995, 2025).
infection (continued). "Following infection, a reproducible antiviral cytokine response, including a consistent increase in CXCL10, IL-6, IFN-λ1, IFN-λ2/3, and IFN-β, was detected across all models." (PMID 39981254, 2025). "The cerebral migration of CD8+ T cells depend on chemokines CXCL9 and CXCL10 abundantly secreted by cerebrovascular endothelial cells after infection." (PMID 41422632, 2025). "This infection is associated with strong activation of IFN signaling, as became evident from gene transcriptional alterations and extensive CXCL10/IP-10 secretion." (PMID 40668059, 2025). "Macrophages and monocytes produce high levels of chemokines (CCL2, CXCL8, CXCL10, etc.)that can recruit other innate and adaptive immune cells to the site of infection." (PMID 40472051, 2025). "C-X-C Motif Chemokine Ligand 10 (CXCL10) is a chemokine-induced in response to inflammation or infection that plays an important role in mediating lung injury." (PMID 40778772, 2025). "The IL- 1β/IL- 1RA and CXCL8/CXCL10 ratios emerge as promising biomarkers to distinguish between infection and inflammation, with potential in targeted wound care." (PMID 40200385, 2025). "In the lungs, CXCL1 was significantly higher in the SFV-only infection at day 3, while CXCL10 was higher at 5 dpi." (PMID 39817772, 2025). "NuRD is involved in silencing of ISG genes, including PD-L1 and CXCL10, in epithelial cell upon long-term infection." (PMID 40717771, 2025). "We observed that pre-infection secreted CXCL10 protein concentrations were 3.32-fold lower in SE compared to NSE (p=6.9e-04) and 2.88-fold lower compared to HC (p=1.0e-01)." (PMID 41279354, 2025). "In this USUV infection model, cytokines CXCL10, CCL11, CXCL1, and G-CSF peaked in the brain at later time points." (PMID 41472308, 2025). "Specifically, CCL3 and CCL4 are implicated in modulating leukocyte recruitment and potentially down-regulating CCR5 expression on DCs, while CXCL9 and CXCL10 are crucial for directing Th1/Tc1-activated lymphocytes and NK cells to the infection site." (PMID 40825006, 2025). "We observed that these post-infection differences were associated with lower pre-infection IFN-stimulated gene (ISG) expression and protein levels of the ISG CXCL10." (PMID 41217821, 2025). "As a pro-inflammatory chemokine, CXCL10 plays an important role in the antiviral immune response, recruiting immune cells to sites of infection or inflammation." (PMID 39861921, 2025). "At both 8 and 16 h post infection, CXCL-10 levels were significantly higher following infection with GeorgiaΔA151R (p < 0.0001)." (PMID 40707000, 2025). "The chemotactic agents CXCL9 and CXCL10 attract cells to the infection site, which secrete more pro-inflammatory cytokines, such as TNF-α, IL-1β and IFN-γ, amplifying the process and exacerbating the Th1 response." (PMID 40608568, 2025). "In the HPC both WT and IL-4R┴ had elevated CXCL-10 following infection and decreased CXCL-10 after Iloprost treatment compared to untreated infected mice." (PMID 40977748, 2025). "Recent observations show that CXCL10 is produced by antigen-presenting cells and activated macrophages during infection." (PMID 40164948, 2025). "We found that interferon-stimulated genes, crucial for restricting respiratory virus replication early after infection, such as CXCL10, CXCL9, CXCL11, OAS1, OASL, and ISG15, were significantly upregulated in PCLS 72 h post-infection." (PMID 41239423, 2025). "Our work demonstrates that human retinal organoids have the capacity to respond to T. gondii tachyzoites, with developing and matured organoids up-regulating CCL2 and CXCL10 transcripts at multiple time points following infection." (PMID 40137771, 2025). "Flow cytometry analysis confirmed that PNAG induces the formation of CD14+CXCL10+ monocytes that migrate to the site of infection and trigger the innate immune response against S. aureus." (PMID 40745039, 2025).